RNY4P24 (RNY4 pseudogene 24)
Gene: Miscellaneous RNA gene on chromosome 13 (52,400,004 to 52,400,099, forward strand). Ensembl gene ENSG00000199605.
Homologues: Orthologues: chimpanzee Y_RNA (100% identical), macaque Y_RNA (97% identical), guinea pig Y_RNA (91% identical), guinea pig Y_RNA (90% identical), guinea pig Y_RNA (89% identical), guinea pig Y_RNA (86% identical). Paralogues in human: RNY4P14 (91% identical), RNY4P7 (91% identical), RNY4 (90% identical), RNY4P10 (88% identical), RNY4P17 (88% identical), RNY4P6 (88% identical), Y_RNA (88% identical), Y_RNA (86% identical), RNY4P13 (85% identical), RNY4P19 (85% identical), RNY4P25 (85% identical), RNY4P3 (85% identical), and 90 more.